TNF (tumor necrosis factor)
Diseases named in the same sentence as TNF in open-access papers (continued):
Sharing a sentence is not in itself a finding about the gene and the disease.
infection (continued). "Our results demonstrated that increasing infection doses could significantly decrease Bcl-2 expression, raise Bax mRNA level, and elevate TNF-α and cleaved caspase-3 protein levels versus control cells." (PMID 37641004, 2023). "Contrarily, in later phases of infection the induction of apoptosis is indeed induced through TNF-α and may be favorable for the pathogen to exit the cell and infect neighbor cells." (PMID 38112844, 2023). "RBAC can also stimulate cytokine secretion in macrophages, especially TNF-α and IL-6, to initiate inflammation during infection and activate autophagy-related proteins (Beclin-1, Atg5, Atg12, Atg16L) for clearing cellular debris and regulating inflammatory responses." (PMID 37687141, 2023). "However, we noticed that the lungs of Gr1-depleted mice showed augmented levels of cytokines related to Th1 (TNF-α) and Th17 (IL-6 and IL-17) profiles at 2 weeks after infection." (PMID 36776848, 2023). "In (F–O), B6.Nlrc4–/–Casp11–/– mice received 200 μg of either TNFα neutralizing antibody (teal, n=12) or isotype control antibody (maroon, n=13) by intraperitoneal injection daily from 1 day before infection through sacrifice at 2 days post-infection." (PMID 36645406, 2023). "During the acute phase of Schistosoma infection, before parasite oviposition (approximately 5–7 weeks post-infection), immune responses are largely of the CD4+ Th1 type, associated with increased numbers of M1 macrophages that produce IL-12, IL-6, TNF-α and NO." (PMID 36601859, 2023). "This association is more frequent after anti-tumor necrosis factor alpha (TNFα) inhibitor therapy in patients with TAK, with increased risk up to 25 times induced by reactivation and dissemination of Mycobacterium TB from latent foci of infection." (PMID 37455309, 2023). "Pro-inflammatory cytokines, IL-1β and IFN-γ, promote the output of innate immune effector cells to address infection at the expenses of reduced bone marrow erythropoiesis, however, TNF-α and IL-1β facilitated the expansion and differentiation of stress erythroid progenitor cells in the spleen." (PMID 37180169, 2023). "Our previous study found that infection with meningitic E. coli can significantly increase the expression of chemokines and cytokines, such as IL-6, IL-1β, TNF-α, CXCL3, CXCL2, and C-C motif chemokine ligand (CCL) 2, and some chemokines remain at high levels in the blood and brain for a long time." (PMID 37445610, 2023). "TNF-α is a proinflammatory cytokine released after mycobacteria make initial contact with macrophages, and it activates naive macrophages and various T cells to prevent bacterial dissemination during the early stage of infection." (PMID 36795721, 2023). "This short-term increase in ROS may be a protective action by the host against a potential infection threat coming from the gut lumen, which the host perceives via elevated bacterial metabolites and elevated inflammatory cytokines such as TNFα." (PMID 36830627, 2023). "The production of IL-12 from cDC was significantly higher than that from pDC at 4 h post-infection (p = 0.0003), whereas the secretion of TNF-α from pDC was significantly higher than that from cDC at 4 and 12 h post-infection (p = 0.045 and 0.034, respectively)." (PMID 36977141, 2023). "As time passes after infection, the serum concentration of TNF-α produced by lymphocytes decreases, indicating that dogs with CME may be in the subclinical phase of the disease." (PMID 37627021, 2023). "Enhanced TNF production in response to LPS after infection with an infectious agent unrelated to bacteria might result from enhanced TLR4 expression, although such an increased TLR4 expression was at best modest after LDV infection." (PMID 37240201, 2023). "However, in two rat studies with Haemophilus influenzae meningitis induced by intraperitoneal injection, it was shown that both in serum and in cerebrospinal fluid, ACAAs against IFNγ and tumor necrosis factor (TNF)-α were induced during the infection." (PMID 38203686, 2023).
infection (continued). "Indeed, during the initial phase of the infection, it was observed that the expression of iNOS and TNFα genes in the spleen was significantly enhanced by HDRsEf1." (PMID 37836523, 2023). "Furthermore, virulent T. gondii strains with the same allelic combinations for these proteins were able to induce higher levels of inflammatory cytokines, such as IFN-γ, IL-12, IL-17, and TNF-α, during early infection in mice." (PMID 38115102, 2023). "Decreased iNOS, TNF-α, IL-6, and IL-12 levels after miR-148a mimic transfection in SL suggests a negative regulatory role of this miR, which can act directly or indirectly in immune responses to infection by L. infantum." (PMID 36719867, 2023). "In contrast, infection with the sp or 5μmF Mtb resulted in only infected cells secreting TNF-α." (PMID 36852737, 2023). "However, at 30 days post-infection, TNF-α, IL-6, KC, CCL3, CCL2, CCL20, CXCL11, CCL11), CCL27, CXCL5, CXCL12 and CCL5 were all significantly higher in the BAL fluid of Duox1 KO compared to WT mice." (PMID 36936954, 2023). "However, the levels of IFN-γ, TNF-α, IL-17, and IL-1β were similar in spleens of control and B cell MHCII deficient mice two weeks post-infection." (PMID 37721965, 2023). "In addition, KEGG pathway analysis of the shared DEGs show enriched in inflammation-related processes including IL-17 and TNF signaling, as well as response to infection." (PMID 38155174, 2023). "Furthermore, type I IFNs can synergize with TNF in both a paracrine and autocrine manner to strongly induce and maintain immune responses during infection." (PMID 37461589, 2023). "Interestingly, ZIKVMR766 infection stimulated higher TNF-α and IL-6 levels than mock-infected cells at the initial stage of infection, i.e., 12 hpi (p < 0.001 and p = 0.4567, respectively), whereas ZIKVPE243 failed to induce significant changes." (PMID 37376550, 2023). "The previous characterization of M35 indicated an antagonism of M35 with NF-κB based on (i) M35-mediated downmodulation of induction of an artificial NF-κB luciferase reporter and (ii) correlation of M35’s phenotype with reduced levels of proinflammatory TNF-α in macrophages at 16 h post-infection." (PMID 37289084, 2023). "We also demonstrated that the circulating CMs were the most frequent cellular source of TNFα among blood monocytes and DCs, while the TNFα at the site of infection may come from both CMs and the IMs (both subsets found in increased frequencies)." (PMID 36752598, 2023). "The upregulation of the expression level of IL-1β, TNF-α, and Myd88 indicates that GF-7 supplementation might induce an immune response in M. salmoides, and enhance the body’s resistance to foreign infection." (PMID 37333660, 2023). "In response to LPS, macrophages play an active role in inflammatory responses by releasing pro-inflammatory cytokines, including TNF-, IL-1, and IL-6, as well as inflammatory factors, such as NO, which recruit additional immune cells to infection or tissue injury sites." (PMID 36678181, 2023). "Lactiplantibacillus plantarum 0111 oral pretreatment up-regulates ISG transcription 7 days after H9N2 infection while elevating CD3+CD4+TNF-α+T lymphocyte percentage and CD3+CD8+TNF-α+T lymphocyte percentage in the spleen and enhancing adaptive immunity to the virus." (PMID 37928517, 2023). "We found that MSAD-1 treatment exerted enhanced productions of two inflammatory cytokines, TNF-α and IL-6 in J774A.1 cells in a dose dependent manner, suggesting that it could elicit immune response of innate cells in infection of mycobacteria." (PMID 37901833, 2023). "Infection with virulent ASFV isolates often results in an exacerbated immune response, associated with elevated serum levels of pro-inflammatory cytokines (IL-1α, IL-1β, IL-6, TNF, CCL2, CCL5 and CXCL10)." (PMID 36680273, 2023). "TNF is processed into TNF-α, which promotes inflammation at the site of infection via vasodilation." (PMID 37682929, 2023).
infection (continued). "In experimental models infected with L. major, BNI isolated, using normally resistant B6 wild mice and mice with TNF B6 deficiency (B6.TNF−/−), progression to a severe or lethal infection profile was reported in the absence of TNF." (PMID 37235324, 2023). "Indeed, infection of BMDMs with ΔflaA L. pneumophila resulted in gradual secretion of TNF, plateauing at about 10 to 12 hours post-infection." (PMID 37279255, 2023). "Finally, TNFα release was significantly elevated only in the small group of pre-exposed individuals with past asymptomatic infection who were analyzed (n=5, Group 3)." (PMID 37885896, 2023). "The interactions between TNFα and various immune markers highlight the intricate balance between proinflammatory signals, antiviral responses, immune cell activation and the immune system’s attempt to control the infection." (PMID 38137381, 2023). "As expected, infection significantly induced IL-1β, TNF-α and IL-6 placental secretion." (PMID 36982317, 2023). "This was performed by collecting and analyzing the culture supernatants of lung explants infected by Fth LVS, Fth LVS ΔiglC, Fth A-660 and F-W12 24 h, 48 h and 72 h post infection to determine the levels of cytokines and chemokines (e.g. IL-1β, IL-6, TNF-α, IL-8, G-CSF, MCP-1, IP-10 and VEGF)." (PMID 37492528, 2023). "If microglia are activated rapidly following infection or insult, they can release cytotoxic molecules such as proinflammatory cytokines (e.g., interleukin (IL)-6, IL-1β, tumor necrosis factor (TNF)-α), reactive oxygen species (ROS) and proteinases to induce neurotoxicity and neuronal apoptosis." (PMID 37676534, 2023). "The infection of macrophages with M. tuberculosis, in the presence or absence of TNF, causes apoptosis of the cells associated with a reduction in Fas expression." (PMID 38112844, 2023). "Similarly, on day 7 after infection, the levels of TNF-α, IL-6, and IL-10 were higher in ΔPbMAP1-infected mice." (PMID 37563696, 2023). "However, when the infection occurs in pregnant women, there is an increase in the production of IL-10, IL-6, IL-17, TNF-a, IFN-a, and IFN-g." (PMID 37376620, 2023). "TNF-α and IL-1β display bimodal patterns of stimulation recognized as essential factors for recruiting phagocytes and initiating the immune response at the infection site." (PMID 37569767, 2023). "IL-6 and tumor necrosis factor (TNF)-alpha was also higher in the infection group." (PMID 36895535, 2023). "After intratracheal infection with Pseudomonas aeruginosa, KO mice showed increased mortality, higher injury scores, more severe inflammation in the lung and kidney, and increased serum TNF-α, IL-1β, and IL-6 levels compared to WT and hTG mice." (PMID 37256132, 2023). "Additionally, TNF-α, another cytokine also produced by immune cells such as macrophages, natural killer (NK) cells and T cells, are important for resistance to infection." (PMID 37954253, 2023). "These discrepancies in TNF expression may be attributed to the stage of infection in which TNF is highly detected in the early stage of infection." (PMID 36670836, 2023). "Next, to determine if the infection could affect the anti-inflammatory capability of the HUCPVCs, we analyzed the TNF-α secretion by LPS-activated J774.1 macrophages co-incubated with CM of HUCPVCs infected at different MOIs with AdhIGF-I and AdGFP." (PMID 37298538, 2023). "have shown that primary neurons from human angiotensin-converting enzyme 2 (ACE2)-expressing mice produce cytokines (e.g., interferon-α (IFN-α), C-X-C motif chemokine ligand 10 (CXCL10), CCL2, IL-6, and TNF-α) after infection with severe acute respiratory syndrome coronavirus 2 (SARS−CoV−2)." (PMID 37767094, 2023). "However, there are indications that can be interpreted as residual infection indicators, such as an increased TNF-α production in activated T-cells and reduced performance." (PMID 37427401, 2023).
infection (continued). "Infection triggered an increase in neutrophil accumulation in the liver; these cells produced TNF-α (significantly higher in females after infection), CCL2, and CXCL1, and the percentage of neutrophils producing CXCL1 was significant higher in males and females compared to uninfected mice." (PMID 38179044, 2023). "In one study, it was shown that one hour after in vitro infection with virulent Mtb and stimulation with TNF, neutrophils suppressed the growth of the bacteria by 50–95%, although significant variability in mycobactericidal capacity between donor neutrophils was reported." (PMID 37965344, 2023). "The levels of TNF-α induced by infection would be worthy of investigation in detail." (PMID 36730424, 2023). "Tumor necrosis factor-α has essential roles as an infection-fighting agent, so patients require close monitoring due to risk of developing infections, and increased risk of cancer may also be a concern." (PMID 36960343, 2023). "Furthermore, infection with a virulent BoHV-1 isolate triggered increased serum levels of IL-10, which paralleled the peak of TNF." (PMID 37112697, 2023). "Casp1/11–/–Casp8+/–Ripk3–/– mice retain Caspase-8 function downstream of both NLRC4 and TNFα and based on our previous experiments with Casp1/11–/– mice, we expected that these mice would be resistant to infection." (PMID 36645406, 2023). "As we previously reported that the infection of macrophages is closely related to their inflammatory state, we investigated the expression of three inflammatory cytokines, TNF, IL1 and IL6, and one immunoregulatory cytokine, IL10, by MDMs and PMs infected with C. burnetii using qRT-PCR." (PMID 36674725, 2023). "The molecular markers we’ve identified, notably NP expression in macrophages and TNF-α secretion during mock infections, offer a valuable schema to categorize patients based on the nature and magnitude of their immune reactions and subsequent inflammasome activations." (PMID 37900310, 2023). "Moreover, OLE attenuates the inflammatory response to LPS or IL-1β/TNFα stimulation, mimicking the infection and inflammatory status of CF patients, in CFBE and primary nasal epithelial (HNE) cells." (PMID 37443798, 2023). "Our findings in Phase II were plausible considering that most studies performed to date, and the Phase I of our study, found a similar severity and risk of infection in patients treated with anti-TNF compared with those without treatment." (PMID 38155275, 2023). "However, as expected, the levels of the proinflammatory cytokine TNFα were significantly increased with infection." (PMID 37615937, 2023). "Plasma from Plasmodium‐infected hosts contains several components of the host's immune response (e.g. IgG, IgE and IgM antibodies, and TNF‐α and related inflammatory cytokines) as well as extracellular vesicles shuttling communication signals between parasites during an infection." (PMID 36448733, 2023). "Tumor necrosis factor-α (TNF-α) is involved in the immune process that fights infection." (PMID 36839279, 2023). "Furthermore, in our experiment, inflammation-related indicators in blood, such as WBC, CRP, IL-6, IL-1β and TNF-α, exhibited varying degrees of elevation since 18 h of infection." (PMID 37587524, 2023). "Subsequently, we measured the daily change of IFN-γ and TNF-α levels in serum to monitor the kinetic response of systemic inflammatory reaction following Eimeria challenge infection since 3-1E is an immunodominant antigen of Eimeria inducing early host inflammatory response." (PMID 37302331, 2023). "In a similar study, PBMC derived macrophages from patients with CL and MCL due to L. braziliensis demonstrated higher values of TNF-α at 48 hours after infection, while another focusing on the same parasite species demonstrated a predominance of TNF-α during active disease." (PMID 36602989, 2023).
infection (continued). "Within a large and heterogenous family of pro-inflammatory cytokines, TNF-α, a primary molecule released during infection and/or inflammation, may trigger sperm phosphatidylserine translocation and the onset of apoptosis." (PMID 36830247, 2023). "However, the synergistic enhancement of TNF production after concomitant exposure to LPS and infection with LDV was much more important in vivo than ex vivo, using macrophages derived from LDV-infected mice." (PMID 37240201, 2023). "Furthermore, acute phase proteins such as haptoglobin, cathelicidins, and peptidoglycan recognition protein were recorded at higher rates during infection; similarly, high levels of IL-1β, IL-8, and TNF-α were expressed." (PMID 36899749, 2023). "The levels of TNFα increased in infected mice compared to uninfected mice during acute infection." (PMID 36676177, 2023). "The transcriptional level of TNF was upregulated in a time-dependent manner after GETV infection." (PMID 37448574, 2023). "Because NETs immobilize and control spreading of pathogens, we next asked whether TNF-mediated NET formation prevented bacterial dissemination from the skin to kidneys on day 3 of the infection." (PMID 37327341, 2023). "This may also act as a counterbalance to pro-inflammatory IFNγ and TNFα that were also upregulated by vaccination, both of which play a role in the clearance of infection but also in pathology development." (PMID 36799886, 2023). "The three inflammatory evidence factors in CTB-OPSBa-immunized mice remained at low levels at all observed time points (p < 0.001), while the other groups showed a significant increase after infection, especially in TNF-α, which reached 250 pg/mL in the PBS and CTB groups." (PMID 36911199, 2023). "Moreover, it was limited to the first 24 hours post-infection and IL-6 and TNFα transcripts decreased in abundance rapidly after an initial burst 2 hours post-infection, suggesting that cytokine release is actively repressed in infected cells." (PMID 37830871, 2023). "Furthermore, the levels of IL6 changed significantly over the 6 week period in the infection group (p = 0.004) and the levels of TNFα also showed significant changes over the weeks in the healthy group (p = 0.013) and in the infection group (p = 0.0098)." (PMID 37762523, 2023). "The authors suggested that carriers of the AG genotype, expressing higher levels of TNF-α, might be better able to control infection and clear the infection early, leading to lower prevalence of persistent joint pain." (PMID 37703107, 2023). "However, there was approximately two folds increase in mRNA expression of IFNγ and TNF-α in BA.5 infection when compared to its parental B.1.1.529 infection." (PMID 37704701, 2023). "Cangma Huadu granules increased the abundance of Bifidobacterium, Parasutterella, Bacteroides, and Faecalibaculum in the intestine of mice at 7 days of PR8 infection, decreased the viral load and lung damage in the lungs, decreased TNF-a and IL-1β levels, and increased IL-10 levels." (PMID 37928517, 2023). "Moreover, while IL-6 and TNFα transcripts tripled in numbers within 2 hours after the infection, they returned to baseline levels within 6 hours." (PMID 37830871, 2023). "To determine whether OI-14-15 regulates noncanonical inflammasome activation directly or by manipulating the TLR-dependent IFN or pro-IL-1β synthesis, we assessed the levels of IFNβ and pro-IL-1β as well as IL-6 and TNF at early stages of infection." (PMID 37041208, 2023). "For the entirety of this study, we infected bone marrow-derived macrophages (BMDMs) with mutant L. pneumophila deficient for flagellin (ΔflaA) in order to bypass the NAIP5 inflammasome response and specifically examine the NAIP5/NLRC4-independent role of TNF signaling in control of infection." (PMID 37279255, 2023).